SPARC (secreted protein acidic and cysteine rich)
Diseases named in the same sentence as SPARC in open-access papers (continued):
Sharing a sentence is not in itself a finding about the gene and the disease.
tumor (continued). "The relationship between SPARC in tumour cells and the expression of angiogenic molecules, as evaluated using a PCR array, indicated that several angiogenic molecules were reduced in Daoy-SP cells compared with controls." (PMID 20087345, 2010). "This suggests that factors other than MMP-9 and VEGF are involved in SPARC-mediated inhibition of tumour growth." (PMID 20087345, 2010). "In our current study, we found that methylation of the SPARC gene is an early event during pancreatic carcinogenesis, which supports the premise that this gene is a tumor suppressor gene." (PMID 20338068, 2010). "This pattern of decreased SPARC levels would suggest an inhibitory role for SPARC in tumor formation." (PMID 20565704, 2010). "The SPARC, a prototype of the matricellular protein family, was shown to have an important role in various aspects of tumourigenesis, including tumour invasion, angiogenesis and tumour growth." (PMID 20087345, 2010). "In melanoma cells, high levels of SPARC expression induce epithelial-mesenchymal transition and increases invasion and tumor progression." (PMID 20525313, 2010). "The MMP-9 induction reversed SPARC-mediated tumour growth inhibition by 50%, with a mean tumour volume of 30% of the empty vector control." (PMID 20087345, 2010). "Our study demonstrates that the anti-tumour effect of SPARC expression in vivo is mediated, at least in part, by anti-vascular effects." (PMID 20087345, 2010). "The secreted protein acidic and rich in cysteine (SPARC) plays a pivotal role in regulating cell-matrix interactions and tumor angiogenesis, proliferation, and migration." (PMID 20338068, 2010). "In order to target both the tumor and stroma compartment we designed a CRAd based on the SPARC promoter since SPARC was shown to be expressed both in malignant and tumor-associated stromal cells." (PMID 19337591, 2009). "Low endogenous SPARC expression was confirmed in the tumor cells of control tumors, and increased expression of SPARC was observed in the SPARC-transfected tumor cells." (PMID 18350569, 2008). "We previously demonstrated that SPARC promotes invasion while concomitantly decreasing tumor growth, in part by decreasing proliferation of the tumor cells." (PMID 18350569, 2008). "The data suggest that SPARC decreases tumor growth by suppressing VEGF expression and secretion, thereby attenuating the VEGF-VEGFR1/2 signaling mechanisms." (PMID 18350569, 2008). "Nevertheless, the relative ease by which in vivo SPARC expression can be manipulated has resulted in continued enthusiasm for its therapeutic potential in highly vascularized tumours." (PMID 18182993, 2008). "We found that the number of factor VIII-positive endothelial cells was significantly lower in the SPARC-expressing tumors indicating that SPARC reduced tumor vascularity." (PMID 18350569, 2008). "In other cancer types, SPARC has been shown to influence tumor growth by altering matrix production, and by decreasing angiogenesis via interfering with the VEGF-VEGFR1 signaling pathway." (PMID 18350569, 2008). "Since SPARC is thought to act as a tumour promoter, these findings point again to Runx2 as a potential tumour suppressor." (PMID 17876328, 2007). "As a regulator of cell-extracellular matrix (ECM) interactions, SPARC is thought to represent a major factor in the ECM remodelling occurring during tumour invasion." (PMID 17201911, 2007). "In the current study, cytoplasmic SPARC in cancer cells was seen in a few cases, and in these cases, immunoactivity was detected in cancer cells mainly localized at the tumor-stroma interface, similar to the pattern of laminin-5γ2." (PMID 17187659, 2006). "The expression of SPARC in tumour tissues was, on average, 4.27-fold increased (95% CI 2.68–5.85) compared to adjacent noncancerous mucosa (P<0.001)." (PMID 15558074, 2004). "A similar clinic–pathologic relationship between SPARC expression and tumour progression has been reported in other malignancies." (PMID 15558074, 2004).
tumor (continued). "The mean expression of SPARC was 4.27-fold increased in tumour tissues, as compared to normal (95% CI 2.68–5.85), which indicated a significant overexpression (P<0.001, by one-sample T-test)." (PMID 15558074, 2004). "The patients were divided into two groups according to the ratio of SPARC expression in the tumour samples, as compared to the adjacent normal tissue." (PMID 15558074, 2004). "Due to the synergistic effects of the enhanced permeability and retention (EPR) effect and Gp60/SPARC-mediated active targeting, this drug carrier demonstrates favorable tumor selectivity and can be enriched in tumor tissues to achieve long-term therapeutic effects." (PMID 42198250, 2026). "To provide confirmatory data on the link between SPARC and IL-23 in patients, we evaluated IL-23 mRNA levels via semiquantitative qPCR in tumor biopsies from the prospective BC cohort, which revealed significantly increased expression of IL-23 in ECM3 + tumors." (PMID 40890836, 2025). "Specifically, SPARC encodes a cysteine-rich acidic matrix-associated protein, belonging to the extracellular matrix protein family, and contributes to ECM organization and tumor invasion." (PMID 41008923, 2025). "As a part of the tumor microenvironment, SPARC mediates ECM-tumor cell communication." (PMID 40810390, 2025). "However, the expression of SPARC is markedly elevated in a variety of pathological conditions, such as inflammation, tumours, obesity, and diabetes, suggesting that it is associated with the development of a variety of diseases." (PMID 40415238, 2025). "Exercise-induced factor (e.g., irisin, SPARC, oncostatin M), released from contracting skeletal muscles, can exert anti-tumor effects by inhibiting cancer cell proliferation, inducing apoptosis, and reducing angiogenesis within the tumor microenvironment." (PMID 40494940, 2025). "Furthermore, the co-localization of CaO2 NPs with Caveolin-1 and SPARC was observed in tumor sections." (PMID 40429837, 2025). "These opposing effects on cell growth, cell migration, and tumor formation suggest that the functions of SPARC are cell-specific and may be dependent on its expression, secretion, and the stage of tumor progression." (PMID 40943659, 2025). "Furthermore, SPARC has been shown to have a pro-invasive function in different tumor contexts, including HCC." (PMID 41008923, 2025). "We hypothesised that the diverse roles of SPARC in a range of cancers and its importance in cancer are contingent upon the specific type of tumour." (PMID 40415238, 2025). "In addition, the primary objective of this study is to investigate the intracellular tumour‐promoting function of SPARC, particularly its role in mediating 5‐FU chemotherapy resistance." (PMID 40415238, 2025). "when targeting the tumor site, HSMONs were endocytosed by tumor cells through another albumin receptor-secreted protein acidic and rich in cysteine (SPARC) and the high GSH level triggered the degradation of HSMONs, thereby releasing the payload only inside the tumor cells." (PMID 41304726, 2025). "In others, mainly ovarian and colorectal cancers, as well as neuroblastomas, SPARC may function as a tumor suppressor." (PMID 40943659, 2025). "In the current analysis, SPARC expression was negatively correlated with memory B cells, which not only participate in anti-tumor immunity through antibody production and T cell activation but also secrete RANKL, promoting bone resorption and local inflammation." (PMID 41018070, 2025). "We identified two tumor-specific ligands of Stabilin-1, SPARC and EGF." (PMID 39516356, 2024). "SPARC induces the synthesis of collagenase, gelatinase, the mesenchymal degrading enzyme, etc., to degrade the matrix and impair the function of the matrix barrier, which ultimately promotes the metastasis of tumor cells." (PMID 38323081, 2024).
tumor (continued). "Our data analysis revealed increased expression of extracellular matrix (ECM) genes within the tumor sample, including an isoform of the Secreted Protein Acidic and Cysteine Rich (SPARC) gene that was expressed 11,676-fold higher than in the adjacent non-malignant tissue." (PMID 38287261, 2024). "Therefore, in the early stages of malignant transformation, SPARC plays a crucial role in tumor cell proliferation and metastasis, angiogenesis, and the remodeling of the extracellular matrix." (PMID 38323081, 2024). "Moreover, IHC staining of the xenograft tumor samples also showed that LCN2 overexpression reduced SPARC protein levels." (PMID 39424639, 2024). "Moreover, albumin exhibits tumor-targeting capacity as it can bind to receptors overexpressed in tumor tissues, such as the cysteine-rich acidic secretory protein (SPARC) and gp60." (PMID 39598513, 2024). "Secreted protein acidic rich in cysteine (SPARC), also called osteonectin, is expressed by macrophages and plays an important role in the development of lymphoid malignancies, since it has been described as either a tumor suppressor or a tumor promoter." (PMID 39057061, 2024). "The function of SPARC relates to and varies with tumor type, cancer cell origin, and the TME." (PMID 39040110, 2024). "Notably observed in normal tissues undergoing development or remodeling processes as well as tissue repair mechanisms; however, in numerous cancerous conditions there is up‐regulation of SPARC expression which significantly contributes to tumor progression." (PMID 38946720, 2024). "For GP60 receptors and SPARC, SPARC was more frequently used to construct albumin-based drug carriers, which might be due to the reason that SPARC is directly expressed and secreted by tumor cells." (PMID 38323081, 2024). "However, SPARC expression was upregulated during angiogenesis, inflammation, wound-healing and tumor development." (PMID 38347494, 2024). "Importantly, SPARC knockdown partially reversed the tumor-promoting effect induced by LCN2 knockdown." (PMID 39424639, 2024). "Increased tumor volume of HCC in nude mice is supported by the overexpression of SPARC." (PMID 37577749, 2023). "Secreted protein acidic and rich in cysteine (SPARC), a multifunctional glycoprotein, is overexpressed in many tumor, but its underlying mechanism in vascular disease has not been elucidated." (PMID 38076208, 2023). "Compared with tumor cells, SPARC appears at higher levels in the stromal cells of the tumor." (PMID 37577749, 2023). "Here, we confirmed the possibility that ICG can bind to both HSA and SPARC, respectively, so these complexes may be ingested into tumor cells." (PMID 36614294, 2023). "SPARC is a multifunctional glycoprotein that can bind calcium and is known to play diverse biological and functional roles in tumor progression; however, its effect on the formation of NETs remains unclear." (PMID 37958984, 2023). "The in vitro study demonstrated that SPARC could increase basic fibroblast growth factor-induced fibroblast migration, thus leading to accumulation of fibroblast in tumor stroma." (PMID 37509139, 2023). "These interactions, which contribute to tumor growth and protection from inflammatory response, are mainly mediated by matricellular proteins, including secreted protein acidic and rich in cysteine (SPARC)." (PMID 38137452, 2023). "Moreover, SPARC stimulates tumor growth and lung colonization after grafting of mouse 4T1 and LM3 TNBC cells in syngeneic mice by promoting cell cycling and expansion of myeloid‐derived suppressor cells." (PMID 36346290, 2023). "We also determined SPARC protein expression in tumor tissue." (PMID 38137452, 2023). "For instance, MIR193A and MIR652 genes’ knock-in may function as a tumor suppressor by inhibiting SPARC function in the EMT phenotype of MESO." (PMID 37509139, 2023).
tumor (continued). "Studies have demonstrated a novel crosstalk between proteases and stromal cellular proteins in the tumor microenvironment through the limited proteolysis of SPARC and have found that SPARC may serve as a possible therapeutic target in TNBC." (PMID 37577749, 2023). "Furthermore, reduced expression of SPARC (Secreted Protein and Rich in Cysteine) regulates the interaction of tumor cells with the extracellular matrix." (PMID 37303738, 2023). "In the TME, SPARC is anti-angiogenic and affects tumor growth, extracellular matrix deposition." (PMID 36895491, 2023). "Another study showed that, in addition to blocking angiogenesis, SPARC may inhibit tumor growth by promoting stromal recruitment." (PMID 37509139, 2023). "Combining the advantage of mannose and albumin, a dual-targeting mannosylated albumin nanoparticle was constructed; this nanoparticle targeting SPARC and MR (mannose receptor) can effectively target both cancer cells and M2 macrophages, leading to the reprogramming of the tumor microenvironment." (PMID 38258072, 2023). "Moreover, SPARC secreted by CAFs promotes tumor growth by inhibiting adhesion of triple-negative BC cells whilst stimulating invasion and metastasis." (PMID 37988189, 2023). "SPARC plays oncogenic or tumor‐suppressive roles, depending on the cancer type." (PMID 36346290, 2023). "Furthermore, SPARC was expressed by different CAF subpopulations in TNBC, and fibroblast‐secreted SPARC exhibited pro‐tumor functions." (PMID 36346290, 2023). "On the contrary, a large number of studies support the promotion by SPARC of tumor angiogenesis." (PMID 37509139, 2023). "In TNBC, mechanistic cell‐based studies support a tumor‐promoting role, suggesting that SPARC could be a candidate stromal therapeutic target." (PMID 36346290, 2023). "Interestingly, AuNRs can also suppress the polarization of macrophages towards the M2 pro-tumor phenotype via SPARC-mediated uptake." (PMID 38258072, 2023). "Through in vitro experiments, we further observed that the detrimental outcomes of ROS on tumor vascular normalization could be mediated through an endocytosis of the caveolin-1 on extracellular SPARC." (PMID 37528424, 2023). "SPARC is present in the tumor microenvironment of many cancers including gastrointestinal cancers." (PMID 37509639, 2023). "SPARC is an extracellular calcium-binding glycoprotein that participates in a variety of cellular processes, including promoting inflammatory cell aging, regulating stromal cell differentiation, and increasing tumor cell invasion." (PMID 37528424, 2023). "Results from studies conducted in SPARC-null mice suggest that SPARC expression in the surrounding tissues may regulate tumor growth." (PMID 38137452, 2023). "Tumor-associated macrophages (TAMs) were identified by CD68, CD14, CD163 and HLA-DRA and cancer-associated fibroblasts (CAFs) were characterized by COL1A1, COL3A1, MMP2, and SPARC." (PMID 37007745, 2023). "The high binding of HSA to SPARC realizes the targeted aggregation of paclitaxel in tumor lesions." (PMID 37577749, 2023). "SPARC staining in tumor cells (>1% stained tumor cells) was observed in 42.4% of TNBC samples." (PMID 36346290, 2023). "Compared to control mucosa, SPARC is highly overexpressed in tumor tissues." (PMID 37577749, 2023). "In addition, the expression of SPARC is positively correlated with tumor response to ab-PTX in head and neck cancer patients." (PMID 36157225, 2022). "Given that adequate research data supporting a direct association between myokines and tumor growth are still lacking, SPARC is one of the most studied myokines in cancer." (PMID 35454797, 2022). "Wnt signaling, mainly by WNT5A, and SPARC enhanced this barrier and facilitated tumor progression." (PMID 36452484, 2022). "On the other hand, COL1A2, COL3A1, COL5A1, FN1, and SPARC may be more involved in tumor progression from stage 1 to stage 2, at which the tumor cells gain the ability to invade surrounding tissues." (PMID 35739492, 2022).
tumor (continued). "In vivo, albumin nanoparticles are recognized by albumin receptor gp60; nab-paclitaxel then penetrates vascular endothelial cells by vesicular transport, enters tumor tissue, and binds to secreted acidic and cysteine-rich protein (SPARC), eventually being retained in tumor cells." (PMID 35719979, 2022). "Targeting nab-paclitaxel to the tumor site was hypothesized to depend on the binding of the albumin-moieties to the protein Secreted Protein Acidic and Rich in Cysteine (SPARC/osteonectin/BM40) overexpressed by fibroblasts in the stromal compartment." (PMID 35214121, 2022). "Although the sample size in SPARC studies in HCC is very small, several studies have shown that SPARC can boost proliferation and migration of tumor cells and that it may be associated with the prognosis of HCC." (PMID 35981080, 2022). "Furthermore, it is described that, depending on the tumor microenvironment, SPARC can act both as a tumor suppressor and as an oncogene." (PMID 36452484, 2022). "Many studies have shown that CXC chemokines attract neutrophils to tumor tissues, promote neovascularization, enhance the expression of pro-metastatic genes (e.g., SPARC, CXCR4, PTGS2/COX2, ANGPT, ALDH, EREG, and EFEMP), and thereby produce a pro-metastatic microenvironment." (PMID 36612163, 2022). "Non-tumor cell genes SPARC and ACTA2 expression correlated with overall survival in MESO cohort." (PMID 35046456, 2022). "Moreover, multiple significant molecular processes involving SPARC have been found in malignant tumors in both the extracellular matrix and tumor microenvironment, including regulation of modulation, anti-adhesion, apoptosis, growth, migration, and invasion." (PMID 35981080, 2022). "Similarly, non-tumor genes SPARC and ACTA2 expression correlated with overall survival in epithelioid subtype." (PMID 35046456, 2022). "The expression of SPARC was also upregulated in breast stromal cells, compared with tumor cells." (PMID 35211625, 2022). "Moreover, it has been showed that regular exercise suppressed colon tumorigenesis in mice, while the anti-tumor effect of exercise was abolished in SPARC knockout mice." (PMID 35454797, 2022). "SPARC is a major contributor to tumor progression, drug resistance, and metastasis." (PMID 35836573, 2022). "Given the role of SPARC in transporting albumin-bound paclitaxel into tumor cells 6, tumoral SPARC may be a more straightforward biomarker for predicting the effectiveness." (PMID 35173526, 2022). "On the contrary, the tumor-promoting effect of SPARC was also reported in GC." (PMID 35368700, 2022). "Moreover, associations between the expression of several genes or proteins and the benefits of paclitaxel, such as CCND1, ABCB1, BCL-2, and SPARC in different tumor types, have been reported in multiple studies 25–29." (PMID 35595817, 2022). "Thus, it should be evident that the response of Abraxane will be enhanced with an increased SPARC level in the tumor." (PMID 35057002, 2022). "However, the link between the SPARC expression profile and patient survival is a matter of debate and seems to depend on the type of tumor." (PMID 35981080, 2022). "In addition, SPARC has been pointed to in the mediation of other effects that are also produced by exercise, such as tumor growth suppression and the anti-inflammatory effect." (PMID 35208200, 2022). "IHC was directed towards finding localizing cell types and assessing numerous types of prognostic variables, including tumor infiltrating lymphocytes, tumor microenvironment proteins, tumor suppressor expression, SPARC positive macrophages, immune checkpoints modifiers, and others." (PMID 35626243, 2022). "Such discrepancy could be attributed to the abilities of SPARC either to promote or to inhibit tumor progression, dependent on cell-type, tumor staging, and various interactions between cell–matrix and tumor-stroma." (PMID 35670884, 2022).